PRKAB2 (protein kinase AMP-activated non-catalytic subunit beta 2)
Description:
Non-catalytic subunit of AMP-activated protein kinase (AMPK), an energy sensor protein kinase that plays a key role in regulating cellular energy metabolism. In response to reduction of intracellular ATP levels, AMPK activates energy-producing pathways and inhibits energy-consuming processes: inhibits protein, carbohydrate and lipid biosynthesis, as well as cell growth and proliferation. AMPK acts via direct phosphorylation of metabolic enzymes, and by longer-term effects via phosphorylation of transcription regulators. Also acts as a regulator of cellular polarity by remodeling the actin cytoskeleton; probably by indirectly activating myosin. Beta non-catalytic subunit acts as a scaffold on which the AMPK complex assembles, via its C-terminus that bridges alpha (PRKAA1 or PRKAA2) and gamma subunits (PRKAG1, PRKAG2 or PRKAG3).
Tractability: Small molecule: a drug acting on it is in phase 2 or 3 trials; a structure with a bound ligand is known; a high-quality ligand is known. PROTAC: ubiquitination databases record sites on it; its protein half-life has been measured; a small molecule that binds it is known.
Target class: Kinase; Protein kinase regulatory subunit; Enzyme
Safety:
Unwanted effects reported when the protein is acted on. In parentheses: how it was acted on, where the effect was seen, and who reports it.
heart disease (cardiovascular system; source: Force et al. (2011))
Gene: Protein-coding gene on chromosome 1 (147,155,106 to 147,173,716, reverse strand). Ensembl gene ENSG00000131791.
Subcellular location (Human Protein Atlas): Nucleoplasm; Cytosol
Pathways (Reactome):
Autophagy: Lipophagy; Macroautophagy
Metabolism: AMPK inhibits chREBP transcriptional activation activity; Carnitine shuttle
Immune System: AMPK-induced ERAD and lysosome mediated degradation of PD-L1(CD274)
Neuronal System: Activation of AMPK downstream of NMDARs
Organelle biogenesis and maintenance: Activation of PPARGC1A (PGC-1alpha) by phosphorylation
Signal Transduction: Energy dependent regulation of mTOR by LKB1-AMPK
Vesicle-mediated transport: Translocation of SLC2A4 (GLUT4) to the plasma membrane
Gene Ontology:
Molecular function: AMP-activated protein kinase activity; protein binding; protein kinase binding
Biological process: cellular response to nutrient levels; positive regulation of cold-induced thermogenesis; signal transduction
Cellular component: nucleotide-activated protein kinase complex; cytoplasm; cytosol; endoplasmic reticulum lumen; nucleoplasm; nucleus
Genetic constraint (gnomAD): Loss-of-function variants: 17 observed, 29.53 expected, observed/expected ratio (o/e) 0.58, 90% interval 0.39 to 0.86. The upper end of that interval is the gene's LOEUF score, 0.86, which puts it in group 3 of 6, group 1 being the genes least tolerant of losing a copy. Missense variants: 269 observed, 339.14 expected, observed/expected ratio (o/e) 0.79, 90% interval 0.72 to 0.88. Synonymous variants: 136 observed, 126.15 expected, observed/expected ratio (o/e) 1.08, 90% interval 0.94 to 1.24.
Gene-disease validity (ClinGen):
ClinGen rates the evidence that PRKAB2 causes each of these diseases.
congenital heart disease (inheritance undetermined): Disputed. A heart disease that is present at birth.
Homologues: Orthologues: chimpanzee PRKAB2 (99% identical), guinea pig PRKAB2 (99% identical), dog PRKAB2 (98% identical), rabbit PRKAB2 (98% identical), pig PRKAB2 (97% identical), rat Prkab2 (97% identical), mouse Prkab2 (97% identical), tropical clawed frog prkab2 (83% identical), macaque PRKAB2 (66% identical), Caenorhabditis elegans aakb-1 (44% identical), Caenorhabditis elegans aakb-2 (43% identical), Caenorhabditis elegans gldi-10 (22% identical). Paralogues in human: PRKAB1 (70% identical).
Diseases named in the same sentence as PRKAB2 in open-access papers:
PRKAB2 is named in the same sentence as 33 diseases in open-access papers, as found by Europe PMC text mining. Sharing a sentence is not in itself a finding about the gene and the disease. The quoted sentences say what the papers report.
schizophrenia (5 papers, 2018 to 2025). A major psychotic disorder characterized by abnormalities in the perception or expression of reality. "The PRKAB2 gene, highly expressed in the right ventricular outflow tract and skeletal muscles, has been associated with schizophrenia." (PMID 37692779, 2023). "Additionally, it indicates that polymorphisms in PRKAB2 are associated with weight gain in patients with schizophrenia or affective disorders treated with antipsychotic drugs (chlorpromazine or olanzapine)." (PMID 40792073, 2025). "Interestingly, a previous study found an association between weight gain upon clozapine or olanzapine treatment in patients with schizophrenia and schizoaffective disorder and a PRKAB2 mutation." (PMID 31819046, 2019). "Therefore, the haploinsufficiency of PRKAB2 may be closely linked to the onset and progression of schizophrenia." (PMID 40792073, 2025). "We found that CHD1L is a candidate for autism spectrum disorder (ASD) and attention deficit hyperactivity disorder (ADHD), whereas PRKAB2 and BCL9 have been associated to schizophrenia." (PMID 29922639, 2018).
breast carcinoma (2 papers, 2021 to 2024). "In this study, the prognostic risk model consisting of six ARGs (VPS35, TRIM21, PRKAB2, RUFY4, MAP1LC3A and LARP1) in breast cancer were identified." (PMID 34001111, 2021). "In conclusion, we identified a novel autophagy-related prognostic risk model consisting of six encoding gene (VPS35, TRIM21, PRKAB2, RUFY4, MAP1LC3A and LARP1) in breast cancer." (PMID 34001111, 2021).
Hypertension (2 papers, 2018 to 2022). The presence of chronic increased pressure in the systemic arterial system. "In this work, we observed, for the first time, that that maternal melatonin therapy prevents hypertension associated with increased expression of Sirt1, Sirt4, Prkaa2, Prkab2, Pparg, and Ppargc1a in adult offspring kidneys." (PMID 29641494, 2018).
type 2 diabetes (2 papers, 2021 to 2026). "The expression level of PRKAB2 in patients with coronary heart disease and type 2 diabetes has always been a research hotspot." (PMID 34138931, 2021).
Adrenocortical Cancer (1 paper, 2024). "Our study sought to evaluate the expression of the PRKAB2 gene as a prognostic biomarker in 63 cases of pediatric adrenocortical tumors and to analyze how efficient Rottlerin is in altering the tumorigenic profile of the NCI-H295R adrenocortical carcinoma (ACC) cell line." (PMID 38539429, 2024).
COVID-19 (1 paper, 2024). A disease caused by infection with severe acute respiratory syndrome coronavirus 2. "In the validation set (GSE190496), we observed a significant increase in the gene expression levels of LSS, HYOU1, ACADVL, PRKAB2, PLIN2, AUP1, and DAP in the COVID-19 group compared to the control group." (PMID 38932215, 2024).
diabetes (1 paper, 2021). "Interestingly, most transcripts namely, Pck2, Prkab2, Pik3r1, Foxo1, Irs1 and Pik3r5 are commonly involved in these pathways and this suggests a significant involvement and contribution of these genes in aberrant skeletal muscle metabolism during diabetes." (PMID 34190986, 2021).
diabetic nephropathy (1 paper, 2024). "The role of PRKAB2 in diabetic nephropathy is not fully understood and further studies are needed to uncover its mechanism of action and potential therapeutic applications." (PMID 38204237, 2024). "The effects of miR-29b and PRKAB2 on inflammatory response and podocyte apoptosis during the progression of diabetic nephropathy were also investigated in an in vitro model." (PMID 38204237, 2024). "In addition, studies on the downstream signaling pathways of PRKAB2 are also necessary to further explore the molecular mechanism of diabetic nephropathy." (PMID 38204237, 2024).
heart failure (1 paper, 2024). Inability of the heart to pump blood at an adequate rate to meet tissue metabolic requirements. "Contrastingly, in this cohort, expression of proteins associated with AMPK-encoding genes (PRKAA1, PRKAG1, PRKAA2, PRKAB1, PRKAB2 and PRKAG2) are significantly higher in oHCM patients, compared with other heart failure aetiologies, and expression of ALDOA is significantly down-regulated." (PMID 39200175, 2024).
hyperuricemia (1 paper, 2021). An abnormally high level of uric acid. "Differentially methylated regions (e.g. HLA-G, IFITM3, PRKAB2) were found in people with hyperuricemia compared to normouricemia in genes relevant for inflammatory cytokine signaling." (PMID 34321071, 2021).
ovarian carcinoma (1 paper, 2014). A malignant neoplasm originating from the surface ovarian epithelium. "PRKAB2 is a regulatory subunit in the AMPK complex and is overexpressed in several cancers, including ovarian cancers." (PMID 24874471, 2014).
sarcoma (1 paper, 2019). A usually aggressive malignant neoplasm of the soft tissue or bone. "Transcription factor genes on chromosome 1 such as NOTCH2 (deletion), PRKAB2 (amplification) and SELL (amplification) also shared similar copy number alterations in all three types of sarcomas." (PMID 30704460, 2019).
cancer (8 papers, 2012 to 2026). A tumor composed of atypical neoplastic, often pleomorphic cells that invade other tissues. "Indeed, close inspection of the TCGA Pan-Cancer Atlas73 demonstrates that the gene encoding β2 (PRKAB2) is amplified in a range of cancers, including breast, liver and lung." (PMID 40052110, 2025). "The PRKAB2 gene produces one of the subunits of the AMP-activated protein kinase (AMPK) complex and has been associated with cancer." (PMID 38539429, 2024). "By contrast, changes in the PRKAB2 gene are more frequent (> 10% in many types of cancer) and are almost invariably amplifications." (PMID 26934201, 2016). "In many cancer genome studies, including the Cancer Cell Line Encyclopedia68, the PRKAA1 and PRKAB2 genes (encoding α1 and β2) tend to be amplified together (P < 0.01), suggesting that there has been selection for amplification of both genes." (PMID 26934201, 2016). "Similar to the α isoforms, an intriguing difference between β1 and β2 concerns the nature of genetic changes in the respective genes (PRKAB1 and PRKAB2) in the cancer genome databases." (PMID 26934201, 2016). "Further work will be necessary to study the role of AMPK in PRKAB2 amplified cancer cells and to characterize the role of PRKAB2 as a putative cancer driver gene." (PMID 24874471, 2014). "As indicated by studies conducted on various types of cancer, lower expression of PRKAB1 and PRKAB2 resulted in increased cell proliferation and enhanced metastatic potential of tumors." (PMID 39001398, 2024).
tumor (8 papers, 2016 to 2026). "Multivariate analysis showed that PRKAB2 expression was an independent prognostic factor when associated with age, tumor weight and volume, and metastasis." (PMID 38539429, 2024). "Lower PRKAB2 gene expression was also associated with death (p = 0.0066), tumor relapse (p = 0.0018), and Sandrini IV staging (p = 0.0197) cases." (PMID 38539429, 2024). "Here, using in vivo genome-wide CRISPR screening, we identified PRKAB2 as a crucial tumor suppressor in RCC." (PMID 41612594, 2026). "Overall, our findings identify PRKAB2 as a critical tumor suppressor in RCC, regulating both protein-protein interactions and lipid metabolism to suppress mitophagy." (PMID 41612594, 2026). "Analysis of CHD1L correlated proteins in the tumor tissue revealed that POLR3C, PRKAB2, SETDB1, GPATCH4, and MSTO1 were the top five ones." (PMID 37033447, 2023). "Analysis of RACGAP1 correlated proteins in the tumor tissue revealed that POLR3C, PRKAB2, SETDB1, GPATCH4, and MSTO1 were the top five." (PMID 36430577, 2022). "Reduced PRKAB2 expression correlated with poor prognosis and aggressive clinical features, whereas overexpression of PRKAB2 markedly inhibited RCC cell proliferation, migration, invasion, tumor growth, and metastasis both in vitro and in vivo." (PMID 41612594, 2026). "Additionally, for the genes PRKAB1, PRKAB2, PER1, PER2, and PER3, methylation was observed in all samples, regardless of the tumor grade." (PMID 39001398, 2024).
infection (1 paper, 2022). The state of being infected such as from the introduction of a foreign agent such as serum, vaccine, antigenic substance or organism. "The differentially expressed proteins post-infection include Akap1, Prkaca, Prkab2, Acaca, Acacb, Aka1, Abcf1, Synj1, Braf, Vcl, and Fhod3, which involve insulin receptor signal, glucagon signal pathway, AMPK signal pathway, and Hippo signal pathway." (PMID 35313969, 2022).
PRKAB2 also shares sentences with these, for which no sentence is quoted: adrenocortical tumors (1 paper); astrocytic tumor (1); attention deficit-hyperactivity disorder (1); autism spectrum disorder (1); cardiomyopathy (1); colorectal adenocarcinoma (1); congenital hypothyroidism (1); coronary heart disease (1); epilepsy (1); glioblastoma (1); head and neck cancer (1); hyperlipidemia (1); idiopathic thrombocytopenic purpura (1); kidney damage (1); lung adenocarcinoma (1); renal cell carcinoma (1); Salmonella Infections (1); schizoaffective disorder (1).